MICB (MHC class I polypeptide-related sequence B)
Diseases named in the same sentence as MICB in open-access papers (continued):
Sharing a sentence is not in itself a finding about the gene and the disease.
tumor (continued). "It is well known that MICA and MICB, which are the ligands of NKG2D and expressed on tumor cells, are important molecules for stimulating the cytoxicity of immune cells, and MICA can easily fall off to soluble MICA (sMICA), which inhibits the activity of NK cells." (PMID 27385218, 2016). "The other molecule that is up-regulated by the drugs is type II transmembrane protein NKG2D, which recognizes MHC class I chain-related molecules (MICA and MICB), as well as UL16-binding proteins (ULPBs) that are expressed on stressed cells, including tumor cells." (PMID 24169587, 2013). "On tumor or stressed cells, this type II transmembrane receptor recognizes ligands, such as UL-Binding Proteins (ULBPs) and MHC class I Chain-related protein A (MICA) and B (MICB), all related to the MHC class I molecules." (PMID 23493799, 2013). "The MICA and MICB proteins are ligands for Natural Killer (NK) group 2, member D (NKG2D) activating receptors on NK cells, CD8+ T cells, and γδ T cells important for the immune-targeted destruction of tumour cells." (PMID 22461998, 2012). "It would be interesting to determine if this behavior is a more general property of MICA- and MICB-producing cells by evaluating whether virus-infected and tumor cells known to secrete MICA and MICB also express NKG2D." (PMID 21477352, 2011). "The secretion of MICA and MICB by cancer cells has been suggested as a mechanism for tumor cell immune escape through the saturation of NKG2D receptors on cytotoxic cells, thus abrogating their ability to recognize tumor cells." (PMID 21477352, 2011). "It is not known if the secretion of MICA and MICB by the tumor cells has any effect on the cancer cells themselves." (PMID 21477352, 2011). "Anti-MICB-CAR-NK cells after PANC-1 revealed that MICB expression was significantly elevated, which predicts that Anti-MICB-CAR-NK cells expressing Anti-MICB-scFv blocked the shedding of MICB protein from the tumor cells and increased the killing ability of NK cells on tumor." (PMID 41516373, 2026). "However, a limitation of the model could be the relatively harsh digestion procedure, which could affect tumor cell viability as well as surface expression of activating ligands MICA and MICB, leading to underestimation of the contribution of these ligands." (PMID 34203549, 2021). "Therefore, macrophages, like tumor cells, proteolytically shed MICA and MICB." (PMID 33424862, 2020). "Similarly, histone deacetylase inhibitor MS-275 enhanced the protein levels of immunostimulatory molecules [MHC class I polypeptide-related sequence B (MICB) and HSP70] in EVs derived from HCC cells, increasing the cytotoxicity of NK cells and anti-tumor response." (PMID 30369925, 2018). "In addition, MICB transcript levels were strongly correlated to those of T-plastin, a factor characteristically expressed by neoplastic T-cells of CTCL; the correlation suggests a relationship to blood tumor burden." (PMID 29190907, 2017). "Similarly, with respect to a possible heterogeneity of MICA and MICB expression within the tumor, our analyses revealed that both the expression as well as the lack of it was homogenous throughout the tumor." (PMID 26902929, 2016). "As HSF1 has been described to regulate the transcription of the NK cell ligands MICA and MICB, we investigated whether treatment of tumor cells with NZ28 and/or NVP-AUY922 alters the cell surface density [mean fluorescence intensity (MFI)] of the NK cell ligands MICA and MICB on tumor cells." (PMID 25854583, 2015). "MICB was identified in the cytosol but not on the surface of primary tumor cells." (PMID 23805414, 2013). "Although NKG2D ligands, including MICA and MICB, are up-regulated during malignant transformation in response to oncogenic activation, their expression can be down-regulated both transcriptionally and non-transcriptionally at the level of tumor cells to escape antitumor the immune response." (PMID 28423623, 2017).
tumor (continued). "Notably, among the five major NKG2DL, MICB was the main NKG2DL regulated by MYC in H2227 cells, while MICA was the main one regulated by MYC in H446 cells, indicating that the regulatory pathways of the same NKG2DL may be different in distinct tumor cells, which required to be further studied." (PMID 35158730, 2022). "Concerning the effect of neddylation on MICB cell surface expression in the absence of relevant changes of mRNA expression, NKG2DL on tumor cells can be regulated by different post-translational mechanisms." (PMID 34482362, 2021). "A second human DNA damage response NKG2D ligand, ULBP2, was induced in the metronomic CPA-treated U251 tumors, but only at day 18, suggesting that MICB, and not ULBP2, contributes to the early onset of U251 tumor regression following metronomic CPA treatment." (PMID 25952672, 2015). "A knockdown of HSF1 decreases the membrane expression of MICB but not that of MICA, whereas a treatment with NZ28 inhibits the expression of both, MICA and MICB on the surface of the investigated tumor cells." (PMID 25854583, 2015). "Treatment of H1339 and MDA-MB-231 tumor cells with 100 nM NVP-AUY922 did not affect the MICA and MICB cell surface density (MFI) (lower part)." (PMID 25854583, 2015). "An important NKG2D ligand is the MHC class I chain A and B (MICA and MICB) and UL16-binding proteins (ULBPs), which are expressed at low levels on the non-malignant cell types while primary tumor cells and tumor cell lines frequently express NKG2D ligands." (PMID 26439264, 2015). "Here we show that MICA and MICB exhibit differential expression patterns among HPV-infected (SiHa and HeLa) and non-infected cell lines (C33-A, a tumor cell line, and HaCaT, an immortalized keratinocyte cell line)." (PMID 21631944, 2011). "Another study used immunohistochemistry to determine that tumor from 82 ovarian cancer patients showed expression of MICA, MICB, and ULBP-2, while none of these molecules was expressed by normal ovarian epithelium." (PMID 20350313, 2010). "Thus, to confirm the lack of MICA and MICB expression in a completely independent set of samples, we analyzed 50 additional MCC tumor samples of 34 patients for their MICA and MICB expression by IHC in conventional tumor sections." (PMID 26902929, 2016). "Notably, protein degradation inhibitors failed to rescue the expression of MICA, MICB, and ULBP3, indicating that the reduced protein levels of MICA, MICB, and ULBP3 in the infected tumor cells were due to the impaired translation of these ligands, and not due to increased protein degradation." (PMID 37753084, 2023). "Our data also indicate that in contrast to other NKG2DL such as MICA, MICB, and ULBP1–3, which are frequently expressed on a broad variety of human tumor cell lines, ULBP4 may be not or only sparsely expressed on the surface of human tumor cell lines." (PMID 29651291, 2018).
cancer (93 papers, 2007 to 2026). A tumor composed of atypical neoplastic, often pleomorphic cells that invade other tissues. "Although the significance of the polymorphism of MICA and MICB remains ill-defined, associations between alleles and autoimmune diseases and cancer has been widely reported." (PMID 34394116, 2021). "Overexpression of microRNA, including miR-17-5p, miR-20a, miR-93, miR-106b, miR-372, miR-373 and miR-520c, resulted in downregulation of MICB expression on the surface of cancer cells and less susceptibility to NKG2D-dependent killing by NK cells." (PMID 32306128, 2020). "Additionally, resveratrol enhances the expression of MHC Class I Polypeptide-Related Sequence A (MICA) and MHC Class I Polypeptide-Related Sequence B (MICB) in cancer cells, making them more susceptible to NK cell-mediated lysis." (PMID 39335671, 2024). "TGF-β1 in an autocrine manner suppressed activating ligands MICB and ULBP3 on cancer cells, of which MICB was necessary for NK cell-induced cytotoxicity." (PMID 41366520, 2026). "Specifically, the inhibition of EHMT2 and TGF-β1 resulted in increased expression of NKG2D ligands (ULBP3 and MICB) on cancer cells in an autocrine manner, resulting in enhanced NK cell-mediated cytotoxicity." (PMID 41366520, 2026). "Its inhibition stimulates NK cell-mediated cytotoxicity by suppressing TGF-β1 and upregulating MICB, and chemokines in cancer cells." (PMID 41366520, 2026). "MICA and MICB expression levels in digestive system malignant tumors are generally higher than in relatively normal tissues." (PMID 40563539, 2025). "From the Cancer Hallmarks perspective, genes such as BMPR2, MICB, CLDN23, and WNT4 were linked to critical processes such as Replicative immortality, resistance to cell death, evading immune destruction, and angiogenesis." (PMID 40863222, 2025). "Previous studies have demonstrated that histone acetylation regulates NKG2D ligand expression such as MICA, MICB, and ULBPs, which are critical for the activation of natural killer (NK) cells and immune surveillance against cancer cells." (PMID 39161385, 2024). "We found the stress MICA/MICB proteins to be downregulated in patients on bevacizumab, and low levels correlated with more prolonged survival, as found in other cancers." (PMID 36968223, 2023). "The results revealed a negative correlation between NUSAP1 and antigen presentation-related molecules (except MICB) in most cancer types, However, in KIRC and THCA, NUSAP1 exhibited a positive correlation with the majority of immune-related molecules." (PMID 37781040, 2023). "In that study, a monoclonal antibody was selected that masks MICA and MICB α3 domain, the site of proteolytic shedding by metzincins, namely ADAMs, preventing loss of cell surface MICA and MICB by human cancer cells." (PMID 32283827, 2020). "The MHC class I chain related-protein A (MICA) and B (MICB) are cancer cell-surface molecules that reflect both cancer cell-centric biological behavior and host immune status." (PMID 29221214, 2017). "In this study, functional analyses of miRNAs predicted to regulate MICB at both UTRs have been evaluated in cancer cell lines." (PMID 28850101, 2017). "The mRNA of MICB in KKU-214 (CCA) were higher than the other cancer cell lines except the immortal cholangiocytes but the protein expression levels were lower." (PMID 28850101, 2017). "The correlation between protein and mRNA expression of MICB in cancer cell lines indicated inverted correlation between protein and mRNA levels." (PMID 28850101, 2017). "Downregulation of NKG2D by high concentration of soluble MICB occurs in cancer patients and during normal pregnancy due to over production by cancer cells or extravillous trophoblasts, respectively, as an active immune-evasion mechanism." (PMID 26745675, 2016). "MiR-10b also targets MICB and promotes resistance of human cancer cell lines to NK cell mediated lysis." (PMID 27356752, 2016).
cancer (continued). "Specifically, we demonstrate that three of the MICB-targeting microRNAs: miR-20a, miR-17-5p and miR-93, also target the same site in the 3′UTR of TWIST1, a transcription factor implicated in cancer metastasis." (PMID 25426550, 2014). "This could involve exploring how targeting MICB might overcome immune evasion strategies employed by cancer cells, to more robust NK cell activation." (PMID 41516373, 2026). "Therefore, an antibody targeting MICA α3 was synthesized to prevent the proteolysis of MICA and MICB from cancer cells, thus allowing the binding of NK cell activating receptor, NKG2D with MICA/B to activate cytotoxic NK cells." (PMID 38726000, 2024). "Variants of the MICB gene, which is located in a highly polymorphic MHC region, are known to be associated with other infections, such as severe acute respiratory syndrome coronavirus 2 (SARS-CoV-2) and cancer." (PMID 37958261, 2023). "In addition, a series of genetic variants in MICA, MICB, NFKBIL1, SLC6A3, CLPTM1L, and TERT have been found to be associated with the susceptibility and prognosis of different cancer types." (PMID 35003220, 2021). "Cancer cells express MICB as the consequence of cellular stress such as genomic damage." (PMID 32306128, 2020). "The stress proteins MICA and MICB are widely expressed by cancer cells due to genomic damage." (PMID 31234517, 2019). "Both ligands induced a downregulation of NKG2D expression and this is suggested to be an immune evasion mechanism performed by hrHPV to lead to cancer development, since the engagement of NKG2D and MICA/MICB plays an important role in cervical and other cancer immune surveillance." (PMID 29976244, 2018). "Our results showed that miR-320 cluster (miR-320a, miR-320b, miR-320c and miR-320d) could down regulated MICB expression in human cancer cells, especially miR-320a that was highly expressed in a CCA cell line (KKU-214)." (PMID 28850101, 2017). "Although the intracellular mediators involved in the regulation of NKG2D ligands expression are still unknown, preliminary data would indicate that the MEK1/ERK, p38 MAPK, PI3K/Akt signaling pathways are involved in MICA and MICB up-regulation in cancer." (PMID 27563819, 2016). "In addition, MICB protein is also expressed mainly in fibroblasts and epithelial as well as in different cancer cell lines such as cervical cancer and myelomonocytic leukemia." (PMID 25626490, 2015). "Similarly, elevated levels of the stress-inducible MHC class I chain-related surface glycoproteins, MICA and MICB, have been found to correlate with cancer stages and metastasis in several carcinomas." (PMID 21712991, 2011). "EHMT2 loss increased AZGP1 and decreased TGF-β1 levels, resulting in the autocrine elevation of NKG2D ligands MICB and ULBP3, chemokines in cancer cells, and the paracrine stimulation of NK cell function." (PMID 41366520, 2026). "Collectively, these results demonstrate that EHMT2-mediated TGF-β1 upregulation in an autocrine manner, inhibits NKG2D ligands (MICB and ULBP3) on cancer cells and, in a paracrine manner, suppresses the cytotoxic ability of NK cells and their migration." (PMID 41366520, 2026). "In vitro, cytotoxicity assays demonstrated that Anti-MICB-CAR-NK cells surpass parental NK cells in eliminating various cancer lines, particularly PANC-1 cells with high MICB expression, and even show improvement in A549 cells with low expression levels." (PMID 41516373, 2026). "Cancer cells which shed their MHC class I chain-related protein A (MICA) and protein B (MICB) can exhibit immune escape properties and ultimately promote rapid cancer progression." (PMID 38726000, 2024). "KRAS-positive tissues revealed weakly significant upregulation of BLNK and downregulation of MICB and TNFSF10 expression when compared to KRAS-negative cancer tissue." (PMID 37869102, 2023).
cancer (continued). "For immunomodulators, we found that the KIFscore was positively correlated with ULBP1, MICB, and CD276, while it was negatively correlated with TNFSF13 and TNFRSF14 in the vast majority of cancers." (PMID 37711200, 2023). "Second, most immuno-stimulators, such as MICB, MICA, CD80, ICOS, CD27, and various TNFSFs (all P < 0.05), were expressed at higher levels in PTPRD/PTPRT mutant cancers, compared with the WT." (PMID 36248841, 2022). "Several studies have shown that the cytotoxicity of NK cells is impaired by miR-10b and miR-20a which target the ligands of NKG2D receptor, MICA/MICB, a MHC class I molecule that is expressed on the surface of cancer cells." (PMID 34179081, 2021). "Among them ADAM10, a catalytically active member of the ADAM family of proteases, is involved in the cleavage of MICA, MICB, and ULBP-2 molecules in various types of cancer cells." (PMID 32269567, 2020). "Cellular miRNAs such as miR-20a, miR-93 and miR-106b which bind to the 3′ UTRs of MICA/B transcripts are upregulated in many human cancers, and are responsible for the downregulation in MICA and MICB protein." (PMID 33352921, 2020). "Among them, ADAM10 cleaves MICA, MICB, and ULBP-2 in different types of cancer cells and its increased expression correlates with cancer progression in MM, malignant pleural mesothelioma, oral squamous cell carcinoma, and gastric cancer." (PMID 32570952, 2020). "The binding of MICA/MICB to NKG2D receptors triggers NK cell-mediated cytotoxicity and enables them to eliminate cancer cells." (PMID 31234517, 2019). "This study has identified a new role of miRNAs in regulation of MICB expression via both 3′-UTR and 5′-UTR sequences applicable for cancer immunotherapy." (PMID 28850101, 2017). "MiR-17-5p, miR-20a, miR-93, miR-106b, miR-373, and miR-520 all target MICA or MICB, two ligands of the NKG2D receptor, and regulate their expression in several human cancer cell lines." (PMID 27356752, 2016). "The human major histocompatibility complex class I polypeptide-related sequence B (MICB) is a protein that modulates the NK and T cell activation through the NKG2D receptor and is related to several diseases including cancer." (PMID 25626490, 2015). "Cancer cells are known to secrete the stress molecules MICA and MICB that activate cytotoxicity by lymphocytes and NK cells through their NKG2D receptor as a mechanism of immunological defense." (PMID 21477352, 2011). "Furthermore, the expression of NKG2D ligand MICB (Fig. EV8F,G) and chemokines CXCL10 and CCL27 (Fig. EV8H) was increased following treatment of cancer cells with BRD4770." (PMID 41366520, 2026). "Furthermore, the expression of CD276, MICB, PVR, TGFB1, and TGFBR1 displayed high correlations with TUBA1B expression in most cancers." (PMID 38589634, 2024). "As most cancer samples were H. pylori-negative, the dysregulation of NKG2D and MICB was likely due to cancer-induced immune evasion." (PMID 38318189, 2024). "Also, in most of the cancers, there was a significant correlation between UBE2C gene expression and C10orf54, CXCL12, IL6R, MICB, PVR, THEM173, and TNFSF13." (PMID 38577722, 2024). "Some molecules associated with γδ T cell activation such as the Butyrophilin (BTN)-family, UL16 Binding Protein (ULBP)-family, MHC Class I Polypeptide-Related Sequence A (MICA) and B (MICB), Annexin A2 (ANXA2), and Apolipoprotein A1 (APOA1 were lower in cancer organoids." (PMID 38090581, 2023). "MICB and ULBP1, as NKG2D ligands, have been shown to be potential loci for targeted cancer therapy." (PMID 37225919, 2023). "Notably, two specific immunostimulators, PVR and MICB, demonstrated significant and positive correlations with WDHD1 across multiple types of cancer." (PMID 37759234, 2023).